ENSG00000285837 (novel protein)
Gene: Protein-coding gene on chromosome 10 (62,374,192 to 62,672,011, forward strand). Ensembl gene ENSG00000285837.
Genetic constraint (gnomAD): Loss-of-function variants: 29 observed, 39.29 expected, observed/expected ratio (o/e) 0.74, 90% interval 0.55 to 1.01. Missense variants: 449 observed, 520.04 expected, observed/expected ratio (o/e) 0.86, 90% interval 0.8 to 0.93. Synonymous variants: 185 observed, 207.24 expected, observed/expected ratio (o/e) 0.89, 90% interval 0.79 to 1.01.